LINC02620 (long independently transcribed non-coding RNA 2620)
Synonyms: BCRT1
Gene: Long non-coding RNA gene on chromosome 10 (104,474,939 to 104,480,274, reverse strand). Ensembl gene ENSG00000225768.
Diseases named in the same sentence as LINC02620 in open-access papers:
LINC02620 is named in the same sentence as 6 diseases in open-access papers, as found by Europe PMC text mining. Sharing a sentence is not in itself a finding about the gene and the disease.
LINC02620 shares sentences with these, for which no sentence is quoted: breast cancer (23 papers); tumor (15); cancer (2); breast tumor (1); Myocardial fibrosis (1); osteosarcoma (1).